U3 (Small nucleolar RNA U3 )
Synonyms: LOC124904153
Gene: Small nucleolar RNA gene on chromosome 17 (44,303,965 to 44,304,203, forward strand). Ensembl gene ENSG00000221496.
Gene Ontology:
Biological process: RNA processing
Cellular component: nucleolus
Homologues: Orthologues: chimpanzee U3 (99% identical). Paralogues in human: U3 (69% identical), U3 (68% identical), SNORD3P1 (67% identical), U3 (66% identical), SNORD3G (66% identical), SNORD3E (65% identical), SNORD3H (65% identical), SNORD3D (64% identical), U3 (64% identical), U3 (63% identical), U3 (62% identical), U3 (61% identical), and 9 more.